ALB (albumin)
Diseases named in the same sentence as ALB in open-access papers (continued):
Sharing a sentence is not in itself a finding about the gene and the disease.
ST Elevation Myocardial Infarction (20 papers, 2019 to 2026). A myocardial infarction that produces elevation in the ST segments of the ECG. "Recent studies have shown that low albumin levels are associated with the NRP in ST-elevation myocardial infarction (STEMI) patients." (PMID 40364067, 2025). "Albumin is an important component of the Naples score (NS), a tool used to predict adverse cardiovascular events, which can also be used to assess long-term mortality risk in patients with ST-elevation myocardial infarction (STEMI) undergoing primary percutaneous coronary intervention." (PMID 38907736, 2024). "The CAR has also been suggested to be a more effective prognostic marker in predicting prognosis of patients with ST elevation myocardial infarction (STEMI) compared to C-reactive protein and albumin alone." (PMID 37834958, 2023). "In the low serum calcium group, the majority of patients were men who had ST-elevation myocardial infarction (STEMI), with lower average hemoglobin, uric acid, serum phosphate, and serum chloride levels; lower LVEF; and higher albumin, BUN, serum magnesium, and LAD levels." (PMID 31781656, 2019). "The study aimed to assess levels of ischemia modified albumin (IMA), malondialdehyde acid (MDA), superoxide dismutase (SOD), and catalase in individuals diagnosed with ST elevated myocardial infarction (STEMI) and non-STEMI." (PMID 34177373, 2021).
analbuminemia (19 papers, 2011 to 2026). "The levels of ALB depend on gene function: to date, 77 of its mutations are known, of which 65 result in bis-albuminemia, and five lead to analbuminemia (<1 g/L)." (PMID 37762957, 2023). "Variants at that position in a CpG sequence result in analbuminemia Bethesda and in albumin Yanomama-2." (PMID 31057599, 2019). "The identification of the defects in the ALB gene causing analbuminemia will contribute to shed light on the molecular basis underlying the trait." (PMID 22174600, 2011). "In our continuing study of this defect, we report here a new case of analbuminemia observed in a 45-year-old man of Lebanese origin living in Switzerland and the identification of the causative mutation within the ALB gene." (PMID 22174600, 2011). "There was speculation that tolerance to albumin deficiency would be characterized by significant upregulation of other plasma proteins to compensate for analbuminemia." (PMID 36979342, 2023). "Another condition that may be associated with altered plasma Zn2+ homeostasis is analbuminemia (albumin deficiency), which is defined as having a plasma albumin level of <1 g L–1." (PMID 30132486, 2018). "Moreover, the albumin gene exhibits a significant degree of DNA mutations causing analbuminemia or alloalbuminemia." (PMID 25674083, 2014). "However, complete albumin deficiency, or specifically the genetic disease congenital analbuminemia, might elevate low-density lipoprotein cholesterol beyond normal ranges." (PMID 39123208, 2024). "Congenital analbuminemia (CAA), resulting from an individual being homozygous for albumin gene mutation, is extremely rare in humans." (PMID 35238481, 2022). "Congenital analbuminemia is an inherited condition characterized by the absence, or by an abnormally low level, of ALB in the blood serum." (PMID 31057599, 2019). "This was based on studies of the relative catabolic rates of IgG and albumin in patients suffering from agammaglobulinemia and analbuminemia." (PMID 25674083, 2014). "Analbuminemia is a rare autosomal recessive disorder manifested by the absence, or severe reduction, of circulating serum albumin (ALB)." (PMID 22174600, 2011). "Humans with congenital analbuminemia (CAA) do not express albumin due to homozygosity for albumin gene mutation." (PMID 36979342, 2023). "We then demonstrated the efficiency of proliferating primary rat hepatocytes in cell fibers not only as cell-based sensors to detect drugs that damage hepatic functions and hepatocellular processes but also as transplants to improve the plasma albumin concentrations of congenital analbuminemia." (PMID 35614100, 2022). "Although these studies suggest a role for albumin in infections, adult patients suffering from the rare disease congenital analbuminemia do not suffer from a severely heightened susceptibility to infectious diseases." (PMID 34154403, 2021). "Moreover, in this study, we have demonstrated that our culture system can be applied to the field of medical transplantation by confirming that, after increasing in number within cell fibers, the primary rat hepatocytes improved plasma albumin concentrations in analbuminemia rats." (PMID 35614100, 2022). "Furthermore, analbuminemia is a rare recessive disorder in which subjects have little or no (<1 mg/ml) circulating albumin caused by a variety of mutations in the albumin gene, and is exhibited only by homozygous subjects." (PMID 25674083, 2014). "Congenital analbuminemia (CAA) is a rare condition in humans that results in the complete absence or nearly complete absence of albumin expression." (PMID 36979342, 2023). "In congenital analbuminemia (CAA), mutations in the albumin gene result in a severe deficiency or absence of plasma albumin." (PMID 32181025, 2020). "Analbuminemia is characterized by the near absence of albumin in the plasma." (PMID 38446837, 2024).
analbuminemia (continued). "Surprisingly, despite the lack of detectable serum albumin, the resulting Alb-/- mouse strains are healthy and breed similarly to their parental strains, while exhibiting changes in serum chemistry consistent with analbuminemia." (PMID 25654695, 2015). "Understanding the mechanisms for tolerance of analbuminemia in CAA patients requires that we acknowledge the multifactorial role of albumin in physiology, with a combination of detrimental effects of analbuminemia which may be partially balanced by some other impacts of albumin’s absence." (PMID 36979342, 2023). "It should also be noted that in human subjects with a genetic disorder called congenital analbuminemia (CAA), no or very low albumin level is detected in plasma." (PMID 37344835, 2023).
cholangiocarcinoma (19 papers, 2009 to 2026). A carcinoma that arises from the intrahepatic biliary tree (intrahepatic cholangiocarcinoma) or from the junction, or adjacent to the junction, of the right and left hepatic ducts (hilar cholangiocarcinoma). "Age and serum sodium, creatinine and bilirubin at diagnosis and albumin at last entry were identified as significant factors associated with death, liver transplant or cholangiocarcinoma." (PMID 21767410, 2011). "According to previous studies, high serum bilirubin level, increased absolute neutrophil counts and low serum albumin level were independent risk factors for tumor recurrence and poor prognosis in patients with cholangiocarcinoma and were important confounding factors for our survival analysis." (PMID 41601773, 2026). "Previous studies have confirmed that albumin, a marker of nutritional status, holds predictive value for postoperative outcomes in cholangiocarcinoma." (PMID 41601773, 2026). "In this case report, a 41-year-old male patient with cholangiocarcinoma received sequential adjuvant chemotherapy with gemcitabine/nanoparticle albumin–bound paclitaxel and gemcitabine/cisplatin." (PMID 37115080, 2023). "In cholangiocarcinoma, pancreatic metastasis (p = 0.023), distant lymph node metastasis (p = 0.044), ALB (p = 0.028) and Hbg (p = 0.003) was relevant to the high incidence of HPD." (PMID 37777758, 2023). "Previous studies have also shown serum albumin level, which may indicate nutritional status, and serum CA 19-9, which may indicate tumor burden, to be prognostic for cholangiocarcinoma." (PMID 36475189, 2022). "Cholangiocarcinoma cell arising from cell proliferation after bile duct injury could be a form of undifferenciated cholangiocyte producing albumin." (PMID 32368289, 2020). "Numerous studies have reported the association between preoperative albumin-bilirubin (ALBI) grade and survival outcomes in patients with cholangiocarcinoma (CCA)." (PMID 40334215, 2025). "The ratio of serum albumin (ALB) to ALP is a powerful index to the prognostication of HCC and cholangiocarcinoma." (PMID 32038998, 2019). "Although, in this study the significant differences between the cholangiocarcinoma and benign biliary tract diseases patients regarding to the values of serum AST, ALT, total bilirubin and albumin were identified." (PMID 21994874, 2011). "However, a substantially lower ALB mRNA level was found in the cholangiocarcinoma tumor group than in the paired nontumor group (Ensembl ID: ENSG00000163631.16, GEPIA2)." (PMID 40186033, 2025).
cholangitis (19 papers, 2014 to 2026). An acute or chronic inflammatory process affecting the biliary tract. "Higher WBC and TBIL and lower serum albumin levels were associated with cholangitis due to stent obstruction after ERCP." (PMID 36052377, 2022). "Serum albumin and cholangitis/cholecystitis tended to be associated with the 30-days-all-cause mortality (p < 0.1)." (PMID 36503588, 2022). "With respect to CR-PF, the independent risk factors were preoperative serum albumin and cholangitis." (PMID 25788941, 2015). "Patient‐related factors included age, sex, primary disease, albumin, preoperative cholangitis, drainage, and non‐naive papilla; intraoperative factors included surgical procedures; postoperative factors encompassed the interval from surgery to bile leak onset." (PMID 40503395, 2026). "Both the groups were comparable with regards to demographics, haemoglobin, serum albumin, preoperative cholangitis and biliary stenting." (PMID 38576960, 2024). "We also found that preoperative cholangitis, low albumin expression, staging (III‐IV), and nerve invasion were obviously associated with the shortened OS, while postoperative treatment was related to the longer OS." (PMID 36825605, 2023). "Univariate logistic regression analysis showed that the patient characteristics such as cholangitis (P = 0.002), preoperative serum albumin (P = 0.000), and texture of the remnant pancreas (P = 0.013) were significantly related to the CR-PF." (PMID 25788941, 2015). "First, in the univariate analysis of Group O, FLRV/BW (< 0.7%) (p = 0.002), PD (p = 0.005), low serum albumin (< 3.5 g/dl) (p = 0.013), blood loss (> 1000 ml) (p = 0.009), PVE (p = 0.036), and preoperative cholangitis (p = 0.031) were associated with the development of PHLF B/C." (PMID 40146336, 2025). "Multivariate logistic regression analysis identified the following statistically significant predictive factors for the immediate development of cholangitis after PTBD: history of cholangitis, recent biliary drainage (≤6 months), elevated C-reactive protein and low serum albumin concentration." (PMID 25148939, 2014). "In the prediction model of this study, the factors that were highly correlated with postoperative cholangitis were operation of time, DBIL (TBIL), albumin, blood glucose, WBC, HB, age, and obstruction location." (PMID 38877118, 2024). "In multivariate logistic analysis, seven potential predictors were identified, including recipient CYP3A4 genotype, cholangitis before LT, GRWR, spleen long diameter, serum albumin, graft volume reduction, and donor CYP3A4 genotype." (PMID 37928356, 2023). "The constructed nomogram included seven parameters, namely recipient CYP3A4 genotype, pre-transplant cholangitis, GRWR, spleen long diameter, serum albumin, graft volume reduction, and donor CYP genotype." (PMID 37928356, 2023).
intracranial hemorrhage (19 papers, 2012 to 2025). Bleeding within the SKULL, including hemorrhages in the brain and the three membranes of MENINGES. "Second, intracranial hemorrhage and lung infection lead to albumin loss." (PMID 36817098, 2022). "Similarly, in patients with intracranial hemorrhage, serum albumin may be associated with acute inflammatory response and the severity of intracranial hemorrhage." (PMID 36079002, 2022). "In contrast, participants with higher diastolic blood pressure and values of albumin and hemoglobin were less likely to encounter symptomatic intracranial hemorrhage." (PMID 36973684, 2023). "Preclinical studies have found that intravenous albumin ameliorates neurological impairment in patients with intracranial hemorrhage." (PMID 36552160, 2022). "The rate of symptomatic intracranial hemorrhage was low (2.9%, 24/830) but more common in the ALB-treated subjects (RR = 2.4, CI95 1.01–5.8)." (PMID 26325387, 2015). "The rate of symptomatic intracranial hemorrhage in the first 24h was low overall (2.9%, 24/830) but more common in the ALB treated subjects (RR = 2.4, CI95 1.01–5.8)." (PMID 26325387, 2015). "Astrocytes exposed to albumin display a number of responses, and it has been postulated that these albumin-evoked responses may contribute to the development of cerebral scarring after brain haemorrhage." (PMID 23346243, 2012).
oral cancer (19 papers, 2015 to 2026). "This study aimed to assess and compare the systemic levels of glutathione (GSH), total plasma protein, and albumin among individuals with tobacco-associated oral cancer, individuals with potentially malignant oral disorders, and tobacco users without oral lesions." (PMID 41737114, 2026). "Similarly, Metgud and Patel reported that oral leukoplakia and oral cancer patients are associated with low albumin levels in comparison with healthy subjects." (PMID 38169924, 2023). "Albumin concentrations showed a similar declining trend, with significantly reduced values in the oral cancer group (3.43 ± 0.47 g/dL) compared to the precancerous (3.84 ± 0.47 g/dL) and control groups (4.00 ± 0.32 g/dL) (p = 0.001)." (PMID 41737114, 2026). "In this sense, this study aimed at preparing and characterizing dastatinib (DAS)/celecoxib (CXB)-loaded bovine serum albumin (BSA) nanoparticles as well as investigating their potential anticancer effects in vitro on SCC-4 oral cancer cell line." (PMID 39937256, 2025). "Two studies reported a lower level of albumin in patients with OSCC whereas the other reported a lower level of albumin in patients with oral cancer." (PMID 37876941, 2023). "BNCT mediated by MID-bovine serum albumin (BSA), another albumin-related boron carrier, also showed long-term retention and anti-tumor effect in a hamster oral cancer model." (PMID 37759639, 2023). "Low levels of albumin post-treatment were considered to have important impacts on oral cancer patients from a prognostic perspective, as indicated by our data." (PMID 35392843, 2022). "The results of this study also found that ALB and PNI may be useful tools to define the risk of death in oral cancer patients." (PMID 32087695, 2020). "Oral cancers are associated with inflammatory mediators, such as IL-6 and TNF, which potentially exert their effects through dual mechanisms, namely, by enhancing the extravasation of albumin across the capillary endothelium at the tumor site and dampening the hepatic production of albumin." (PMID 38476986, 2024). "Moreover, a large-scale prospective study for the nutritional assessment of oral cancer demonstrated that patients with low levels of NRI were associated with worse prognosis in oral cancer and the prognostic performance of NRI was superior to BMI or serum ALB." (PMID 36771348, 2023). "ALB, PNI, NRI were inversely correlated with OS of oral cancer (HR = 0.716; 95% CI: 0.575–0.891; HR = 0.793; 95% CI: 0.633–0.992; HR = 0.588; 95% CI: 0.469–0.738, respectively)." (PMID 32087695, 2020). "Moreover, ALB, PNI and NRI were inversely correlated with the prognosis of oral cancer patients (all P < 0.001)." (PMID 32087695, 2020). "Therefore, this study was done to examine how serum albumin and uric acid were related to individuals who consumed areca or tobacco, a combination of both in OSMF, because early detection may help reduce the morbidity of oral cancers." (PMID 38169924, 2023).
pericardial effusion (19 papers, 2014 to 2025). Fluid collection within the pericardial sac, usually due to inflammation. "Among many other heart complications, it can lead to pericardial effusion by causing increased permeability of albumin across the pericardial membrane that leads to exudative pericardial effusion." (PMID 34786222, 2021). "We discuss the pathophysiology of pleural and pericardial effusions in thyroid disease, which is thought to involve increased capillary permeability and changes in oncotic pressure related to albumin." (PMID 38813286, 2024). "The results showed that preoperative moderate/severe pericardial effusion, preoperative celiac trunk involvement, CPB time > 180 min and decreased early postoperative serum albumin were independent risk factors for severe adverse outcomes in patients with PHD." (PMID 36401191, 2022). "For patients aged <40 years, factors correlating with poor progression-free survival (PFS) were pleural or pericardial effusion, regimen, albumin level and therapy response." (PMID 29348421, 2018). "Preoperative moderate/severe pericardial effusion, preoperative celiac trunk involvement, CPB time > 180 min and decreased early postoperative serum albumin were identified as independent risk factors for severe adverse outcomes in patients with postoperative HD." (PMID 36401191, 2022). "Preoperative moderate/severe pericardial effusion, preoperative celiac trunk involvement, cardiopulmonary bypass (CPB) time > 180 min and decreased early postoperative serum albumin were identified as independent risk factors for severe adverse outcomes in patients with PHD." (PMID 36401191, 2022). "Pleural or pericardial effusion, aaIPI score, regimen, LDH increased, albumin level, therapy response and mediastinal mass were all related with poor overall survival (OS)." (PMID 29348421, 2018). "HIV-uninfected patients with TB pericarditis are at a higher risk for unfavorable outcomes when presenting with low serum albumin, with large pericardial effusions, and without cardiovascular disease." (PMID 27899066, 2016).